OTUD3 (OTU deubiquitinase 3)
Description:
Deubiquitinating enzyme that hydrolyzes 'Lys-6'- and 'Lys-11'-linked polyubiquitin. Also hydrolyzes heterotypic (mixed and branched) and homotypic chains. Important regulator of energy metabolism. Glucose and fatty acids trigger its nuclear translocation by CBP-dependent acetylation. In the nucleus, deubiquitinates and stabilizes the nuclear receptor PPARD regulating the expression of various genes involved in glucose and lipid metabolism and oxidative phosphorylation. Also acts as a negative regulator of the ribosome quality control (RQC) by mediating deubiquitination of 40S ribosomal proteins RPS10/eS10 and RPS20/uS10, thereby antagonizing ZNF598-mediated 40S ubiquitination.
Synonyms: KIAA0459; DUBA4
Tractability: PROTAC: ubiquitination databases record sites on it.
Target class: Enzyme; Hydrolase
Gene: Protein-coding gene on chromosome 1 (19,882,395 to 19,912,945, forward strand). Ensembl gene ENSG00000169914.
Subcellular location: Cytoplasm; Nucleus
Subcellular location (Human Protein Atlas): Cytosol; Intermediate filaments; Nucleoplasm
Pathways (Reactome):
Metabolism of proteins: Ovarian tumor domain proteases
Signal Transduction: Regulation of PTEN stability and activity
Gene Ontology:
Molecular function: cysteine-type deubiquitinase activity; protein binding
Biological process: cellular response to nutrient levels; negative regulation of phosphatidylinositol 3-kinase/protein kinase B signal transduction; protein deubiquitination; protein K11-linked deubiquitination; protein K27-linked deubiquitination; protein K48-linked deubiquitination; protein K6-linked deubiquitination; protein stabilization
Cellular component: cytoplasm; nucleus; cytosol
Genetic constraint (gnomAD): Loss-of-function variants: 16 observed, 29.07 expected, observed/expected ratio (o/e) 0.55, 90% interval 0.37 to 0.84. The upper end of that interval is the gene's LOEUF score, 0.84, which puts it in group 3 of 6, group 1 being the genes least tolerant of losing a copy. Missense variants: 346 observed, 343.91 expected, observed/expected ratio (o/e) 1.01, 90% interval 0.92 to 1.1. Synonymous variants: 144 observed, 129.01 expected, observed/expected ratio (o/e) 1.12, 90% interval 0.97 to 1.28.
Homologues: Orthologues: chimpanzee OTUD3 (99% identical), macaque OTUD3 (98% identical), pig OTUD3 (95% identical), dog OTUD3 (94% identical), guinea pig OTUD3 (89% identical), rabbit OTUD3 (87% identical), mouse Otud3 (82% identical), rat Otud3 (79% identical), tropical clawed frog otud3 (59% identical), zebrafish otud3 (49% identical), Drosophila melanogaster otu (10% identical), Drosophila melanogaster CG3251 (9% identical). Paralogues in human: OTUD4 (21% identical), OTUD5 (20% identical), OTUD6B (13% identical), OTUD1 (13% identical), OTUD6A (12% identical).
Diseases named in the same sentence as OTUD3 in open-access papers:
OTUD3 is named in the same sentence as 60 diseases in open-access papers, as found by Europe PMC text mining. Sharing a sentence is not in itself a finding about the gene and the disease. The quoted sentences say what the papers report.
breast carcinoma (21 papers, 2019 to 2025). "Researchers have identified gene mutations in the breast cancer cell lines involving OTUD3, leading to loss of protein function and accelerating the migration and metastasis of cancer cells." (PMID 38288086, 2023). "Previous study has indicated that the expression level of OTUD3 was downregulated in human breast cancer and was notably associated with PTEN expression." (PMID 31266968, 2019). "Additionally, various loss-of-function mutations and decreased expression of OTUD3 have been reported in malignancies, indicating its clinical significance in breast cancer." (PMID 34575114, 2021). "Inversely, OTUD3 deficiency activated the AKT signaling pathway and propagated the transformation and metastasis of breast cancer cells." (PMID 40469292, 2025). "Whereas miR-520h induced paclitaxel resistance in breast cancer MCF-7 cells by inhibiting the OTUD3/PTEN axis, co-treatment with miR-520h inhibitor and OTUD3 overexpression significantly enhanced the sensitivity of MCF-7 cells to paclitaxel." (PMID 41050073, 2025). "For example, miR-520h binds to OTUD3 to inhibit the expression of OTUD3 protein in breast cancer cells, which in turn enhances the resistance of breast cancer cells to paclitaxel." (PMID 37829187, 2023). "In breast cancer, OTUD3 stabilizes PTEN, inhibiting the PI3K/p-AKT/mTOR pathway and suppressing tumor growth." (PMID 38288086, 2023). "In contrast to its level in breast cancer, OTUD3 is highly expressed in human lung cancer, and its upregulation is associated with unfavorable prognoses." (PMID 36385557, 2022). "OTUD3−/− mice are originally bred to focus on the role of OTUD3 in tumorigenesis of breast cancer and lung cancer." (PMID 35490179, 2022). "OTUD3 exhibits tumor-promoting activity in lung cancer, and conversely shows tumor-suppressing activity in breast cancer." (PMID 34575114, 2021). "This study further elucidated the influence of OTUD3 on BC cell biological function and its molecular mechanism and suggests that OTUD3 should be explored as a therapeutic target in breast cancer." (PMID 32571254, 2020). "Our findings suggested that miR-520h increased breast cancer cell resistance to paclitaxel mainly through inhibiting OTUD3 expression, which subsequently attenuated PTEN stability and activated the AKT signaling pathway." (PMID 32775453, 2020). "MTS assay for proliferation detection, detection of apoptosis induced by cisplatin and colony formation assay were employed to investigate the functional effects of OTUD3 on breast cancer cells." (PMID 32571254, 2020). "Prognostic analysis showed that high expression of miR-520h is an indicator of poor prognosis for breast cancer patients, and breast cancer patients with high expression of OTUD3 and PTEN had a better prognosis than those with low expression." (PMID 32775453, 2020). "Compared to breast cancer tissues of PyMT/OTUD3 WT mice, decreased PTEN protein level and increased p-AKT (Ser-473) level were observed in breast cancer tissues of PyMT/OTUD3 KO mice." (PMID 31266968, 2019). "Our previous data demonstrated that OTUD3 acts as a tumor suppressor in breast cancer by maintaining PTEN stability and OTUD3 transgenic (TG) mice are less prone to tumorigenesis of breast cancer." (PMID 31266968, 2019).
breast carcinoma (continued). "Here, we demonstrate that in vivo deletion of OTUD3 indeed promotes breast cancer development in mice, but by contrast, it slows down KrasG12D-driven lung adenocarcinoma (ADC) initiation and progression and markedly increases survival in mice." (PMID 31266968, 2019). "As expected, deficiency of OTUD3 accelerated the development of mammary tumor in MMTV-PyMT transgenic mice, which was consistent with our previous conclusion in OTUD3 transgenic mice." (PMID 31266968, 2019). "In breast cancer, OTUD3 suppresses tumorigenesis and progression by stabilizing PTEN." (PMID 38351178, 2024). "Recently, we demonstrated the OTU (ovarian tumor protease) family member OTUD3 (OTU domain-containing protein 3) suppresses the development of breast cancer via maintaining the stability of PTEN, but promotes the development of lung cancer through stabilizing GRP78." (PMID 35490179, 2022). "A log-rank analysis indicated that high miR-520h expression in the tumor tissues predicted poor survival in breast cancer patients (P = 0.011), whereas patients with high expression levels of OTUD3 (P = 0.010) and PTEN (P = 0.029) had better survival rates than those with low expression levels." (PMID 32775453, 2020). "In the present study, OTUD3 knockout mice were generated and crossed with spontaneous breast cancer mice (MMTV-PyMT mice) and inducible NSCLC mice (Kras G12D mice), and we find that OTUD3 deletion results in increased susceptibility to breast cancer, but decreased susceptibility to NSCLC." (PMID 31266968, 2019). "Although evidence based on OTUD3 transgenic mice model showed the tumor suppressive role of OTUD3 in breast cancer, whether deletion of OTUD3 in vivo could promote the occurrence and development of breast cancer remains mysterious." (PMID 31266968, 2019). "Whereas, in breast cancer cells OTUD3 was hardly detected to be colocalized with GRP78 in the ER." (PMID 31266968, 2019). "However, OTUD3 tends to show low expression in breast cancer tissues or cells and may be a novel cancer biomarker for metastasis and poor prognosis in breast cancer patients." (PMID 41050073, 2025). "Therefore, miR-520h might directly mediate the expression of OTUD3 at the transcriptional level in breast cancer cells." (PMID 32775453, 2020). "Thus, our results indicated that miR-520h could regulate drug resistance to paclitaxel by targeting OTUD3 in breast cancer cells." (PMID 32775453, 2020). "Therefore, our research indicates that miR-520h may be one of the prognostic indicators for breast cancer patients and further confirmed the miR-520h-OTUD3-PTEN regulatory axis in breast cancer." (PMID 32775453, 2020). "OTUD3/PTEN axis inhibits the proliferation and metastasis of breast cancer cells by inhibiting the transduction of the PI3K/AKT pathway." (PMID 41050073, 2025). "In breast cancer, for instance, OTUB1, YOD1, OTUD5, OTULIN, TNFAIP3, and ZRANB1 drove chemoresistance, whereas OTUD1 and OTUD3 were sensitized to chemotherapy." (PMID 40469292, 2025). "Studies have confirmed that the OTUD3/PTEN axis inhibits the proliferation and metastasis of breast cancer cells by inhibiting the transduction of the PI3K/AKT pathway." (PMID 41050073, 2025). "However, OTUD1 and OTUD3 could curb the progression of breast cancer." (PMID 40469292, 2025).
breast carcinoma (continued). "Early evidence suggests that OTUD3 functions as a deubiquitinase for PTEN, interacting with PTEN to enhance its stability, thus inhibiting the progression of breast cancer." (PMID 39097608, 2024). "OTUD3 inhibits the activation of the AKT pathway by deubiquitinating PTEN and suppresses tumour progression in breast cancer (BC), colon cancer and cervical cancer." (PMID 38685067, 2024). "Among the ∼100 DUBs, several members, such as A20, USP43, OTUD1, OTUD3 and USP13, have been identified as key regulators in breast cancer." (PMID 37608493, 2023). "OTUD3 interacts with PTEN in the cytoplasm, deubiquitinates and stabilizes PTEN, ultimately inhibiting tumor growth and metastasis in breast cancer." (PMID 37829187, 2023). "For example, OTUD3 and USP13 can deubiquitinate and stabilize the tumour suppressor PTEN, thereby playing a suppressing role in breast cancer." (PMID 37608493, 2023). "OTUD3 transgenic mice exhibit higher PTEN expression and show a reduced tendency for breast cancer tumorigenesis." (PMID 36385557, 2022). "The reduction in OTUD3 expression, concomitant with decreased PTEN protein levels, correlates with breast cancer aggressiveness and poor prognosis." (PMID 36385557, 2022). "Through proteome‐wide screen of DUB members, USP13 and OTUD3 have been identified as deubiquitinases which directly bind to and stabilize PTEN in breast cancer." (PMID 33155366, 2021). "In our previous study, we showed that OTUD3 exhibited a tumor suppressor role and acted as a specific cytoplasmic deubiquitinase for PTEN in breast cancer." (PMID 32775453, 2020). "The results demonstrated that miR-520h specifically targeted the OTUD3 3′UTR and suppressed the protein expression of OTUD3 in breast cancer cells." (PMID 32775453, 2020). "To investigate it, we next analyzed the colocalization of OTUD3 and GRP78 or PTEN in lung and breast cancer cell lines using immunofluorescence and used Calnexin as a ER marker." (PMID 31266968, 2019). "Reduction of OTUD3 expression, concomitant with decreased PTEN abundance, correlates with human breast cancer progression." (PMID 31266968, 2019). "Further tissue microarray analysis shows that the expression levels of OTUD3 are decreased, concomitant with reduction of PTEN abundance, in human breast cancer, hepatocellular cancer, colon cancer, and cervical cancer." (PMID 31266968, 2019). "Secondly, although OTUD3 can inhibit tumor growth and metastasis by stabilizing PTEN in breast cancer, hepatocellular cancer, colon cancer, and cervical cancer, loss of OTUD3 suppressed the tumorigenesis of lung cancer in vitro and in vivo." (PMID 31266968, 2019). "OTUD3 could deubiquitylate and stabilize the tumor suppressor PTEN in breast cancer at the protein level." (PMID 38539203, 2024). "Furthermore, OTUD3 has been identified as a potent deubiquitinase for PTEN and thus a tumor suppressor in breast cancer." (PMID 36385557, 2022). "Furthermore, the expression levels of OTUD3 and PTEN have been correlated with human breast cancer progression." (PMID 32775453, 2020). "OTUD3 expression in breast cancer tissue was independent of the histological grade (F = 1.736, p = 0.199)." (PMID 32571254, 2020). "Firstly, the expression level of OTUD3 was significantly upregulated in lung cancer tissues compared with adjacent tissues, and the positive correlation between OTUD3 and PTEN detected in breast cancer, hepatocellular cancer, colon cancer, cervical cancer, disappeared in human lung cancer." (PMID 31266968, 2019). "Therefore, our findings showed that miR-520h targeted the OTUD3-PTEN axis to drive paclitaxel resistance, and this miR might be an important potential target for breast cancer treatment." (PMID 32775453, 2020). "OTUD3 regulation by miRNAs has never been illustrated in breast cancer." (PMID 32775453, 2020).
breast carcinoma (continued). "In general, we revealed that OTUD3 functions as a tumor promoter in lung cancer by maintaining the protein level of GRP78, whereas exhibits tumor suppressive role through stabilizing PTEN in breast cancer, hepatocellular cancer, colon cancer, and cervical cancer." (PMID 31266968, 2019).
lung carcinoma (18 papers, 2019 to 2025). "OTUD3 is overexpressed in lung cancer, and the increased expression of OTUD3 is associated with short survival and poor prognosis in lung cancer patients." (PMID 38539203, 2024). "OTUD3 is highly expressed in human lung cancer tissues and is associated with poor patient survival." (PMID 37829187, 2023). "OTUD3 is highly expressed in human lung cancer tissues, and its increased expression is linked to a poor survival rate." (PMID 35884607, 2022). "Strikingly, OTUD3 is upregulated in human lung cancer and elevated expression of OTUD3 is associated with poor prognosis in lung cancer patients." (PMID 31266968, 2019). "However, we recently observed Otud3 transgenic mice are more susceptible to KrasG12D-driven lung cancer, while Otud3 KO mice are less susceptible, indicating an oncogenic role of OTUD3 in lung cancer." (PMID 38539203, 2024). "However, further study showed that Otud3 transgenic mice were more susceptible to KrasG12D-driven lung cancer while Otud3 KO mice were less susceptible, implicating an oncogenic role of OTUD3 in lung cancer." (PMID 37369659, 2023). "OTUD3 promotes lung cancer growth and metastasis by deubiquitinating and stabilizing the glucose regulatory protein GRP78." (PMID 41050073, 2025). "In addition, OTUD3 is also overexpressed in human lung cancer and is associated with poor prognosis in lung cancer patients; OTUD3 deficiency inhibits the oncogenic ability of lung cancer cells, while OTUD3 overexpression promotes the malignant progression of lung cancer." (PMID 41050073, 2025). "But we found that when Rolapitant was added to lung cancer cells, Rolapitant inhibits the deubiquitinating activity of OTUD3, thereby promoting GRP78 ubiquitination and resulting in its degradation." (PMID 38539203, 2024). "In our present study, we identified Rolapitant as an inhibitor of OTUD3 that can also promote ER stress DR5-induced apoptosis of lung cancer cells through disrupting the interaction of OTUD3 with GRP78." (PMID 38539203, 2024). "Rolapitant inhibited the proliferation of lung cancer cells by inhibiting deubiquitinating activity of OTUD3." (PMID 38539203, 2024). "Our previous study indicated that deubiquitinase OTUD3 promoted the progression of lung cancer through stabilizing GRP78." (PMID 38539203, 2024). "Taken together, these results demonstrated that OTUDin3 inhibited lung cancer cell growth, migration and invasion, and induced apoptosis by targeting OTUD3." (PMID 37369659, 2023). "OTUD3 is stabilized in lung cancer cell lines by the deletion of CHIP, and the level of intracellular GRP78 increases, thus promoting lung cancer cell invasion and tumor metastasis." (PMID 37829187, 2023). "Nevertheless, an intriguing puzzle has been suggested following a recent study of the accelerated development of lung carcinomas after deletion of Otud3 in mice." (PMID 36385557, 2022). "Subsequently, their further study showed the oncogenic function of OTUD3 in lung carcinoma and that OTUD3 drives lung cancer progression by stabilizing glucose-regulated protein 78-kDa (GRP78)." (PMID 34380780, 2021). "Although OTUD3 has been identified as an important oncogenic driver in lung cancer carcinogenesis, our study is the first one disclosing the function of OTUD3 in HCC." (PMID 34380780, 2021). "In lung cancer, OTUD3 overexpression induced tumorigenesis by stabilizing glucose-regulated protein 78 (GRP78)." (PMID 32882786, 2020). "USP17 and OTUD3 promote lung cancer stemness through mediating TRAF2/TRAF3 complex and stabilizing GRP78, respectively." (PMID 32549341, 2020). "Several lines of evidence support the concept that OTUD3 exhibits tumor-promoting effect in lung cancer." (PMID 31266968, 2019). "Here, the authors show that OTUD3 also has an oncogenic role in lung cancer by stabilizing the glucose-regulated protein GRP78." (PMID 31266968, 2019).